GRB2 (growth factor receptor bound protein 2)
Diseases named in the same sentence as GRB2 in open-access papers (continued):
Sharing a sentence is not in itself a finding about the gene and the disease.
breast carcinoma (continued). "Next, we compared mRNA levels of these genes in tumor tissues and their matched adjacent normal tissues in breast cancer patients (n = 93) and found CBLB and GRB2 expression were significantly higher in tumor tissues." (PMID 29416005, 2018). "Remarkably, our study indicated CBLB and GRB2 were direct targets of miR-27b, and played important roles in miR-27b-mediated PTX sensitivity in breast cancers." (PMID 29416005, 2018). "We previously reported that in breast cancer, BST-2 renders cancer cells resistance to anoikis through the GRB2/ERK/BIM/Cas3 pathway." (PMID 30514852, 2018). "GRB2 is an adaptor protein which interacts with phosphorylated TGF-β receptor and is critical for mammary tumour growth." (PMID 30087284, 2018). "To characterize GRB2 signalling complexes in HER2+ breast cancer cells, we generated HCC1954 cell lines stably expressing 3xFLAG-tagged GFP and 3xFLAG-GRB2." (PMID 28912526, 2017). "This leads to Grb2-TβRII binding and downstream MAPK signaling that can drive tumor progression in models of breast cancer." (PMID 26267863, 2015). "Among breast cancer cell lines, MCF7 is unique when the measure crs(h = 2) is used to assess the EGFR pathway with GRB2 and MAPK1 ranking highest, while all the other cell lines have EGFR and/or RAF1 as top ranking genes." (PMID 24550933, 2014). "The localization of GRB2 in the nucleus provides a new mechanism for recruitment of MER11 for HDR, which may serve as a potential biomarker for tracking breast cancer." (PMID 38540680, 2024). "In the first stage of the study, the nanoparticles with ASOs targeting Grb2 inhibited the viability of breast cancer cells that overexpressed ErB2, without affecting cell lines with reduced ErB2 expression." (PMID 39272802, 2024). "THSWD could regulated the RNA and protein expression of core targets HRAS, MAPK1, AKT1, GRB2, and MAPK14 for treatment of breast cancer." (PMID 34513708, 2021). "Thus, downregulation of COX2, GRB2 and MEK5 as seen in the ATX-101/AEE788 combination treatment supports the phenotype observed in this pre-clinical breast cancer model." (PMID 31921382, 2019). "In addition, GRB2 and SOS1 have been reported to be overexpressed in breast cancer tissues compared with normal tissues." (PMID 31036036, 2019). "The contribution of the Grb2/Ras/MAP-kinase pathway to the protection by IGF-1 of oestrogen-responsive breast cancer cells from anoikis was tested with U0126 which is a non-competitive inhibitor of MEK1 and MEK2 that prevents activation of ERK1 and ERK2." (PMID 26801096, 2016). "Although the Grb2/Ras/MAP-kinase pathway is not involved in the anoikic resistance of oestrogen-responsive breast cancer cells, its inhibition induces significant cell death which is abrogated almost completely by IGF-1." (PMID 26801096, 2016). "Novel GRB2-interactions (CNAIP and SIT1) with phosphotyrosine located at the ITAM region are critical for activating cytokine promoters as well as viral virus induced mammary tumors." (PMID 23826330, 2013). "Multiple other genes from the driver subnetworks, including GRB2, MED1, MED24, and EPN3 are also located in the proximity of the same amplicon (between 17q12–25), underscoring the significance of this chromosomal region in HER2+ breast cancer." (PMID 22343619, 2012). "Consequently, Grb2 is recruited into the Plexin B1 receptor complex and interacts with p190 RhoGAP via its SH3 domain, which mediates RhoA deactivation and subsequently inhibits the motility of breast carcinoma cells." (PMID 39769452, 2024). "Moreover, a significantly negative correlation between miR-27b and CBLB/GRB2 expression were found in tumor tissues of breast cancer patients (n = 93)." (PMID 29416005, 2018). "Breast cancer cells as exemplified by Hs578T, MDA-MB-231, BT-474 and T-47D have been reported to be inherently resistant to anoikis and it was concluded that this resistance does not involve the PI3-kinase/Akt or Grb2/Ras/MAP-kinase pathways." (PMID 26801096, 2016).
hepatocellular carcinoma (19 papers, 2010 to 2025). A malignant tumor that arises from hepatocytes. "PSMD14 also enhances hepatocellular carcinoma growth and metastasis by inhibiting GRB2 via deubiquitination and stabilizes LRPPRC via deubiquitination." (PMID 38643468, 2024). "The expression of PSMD14 is significantly higher in hepatocellular carcinoma than in normal liver tissues, and the knockdown of PSMD14 expression inhibited hepatocellular cancer proliferation and metastasis by down-regulation of GRB2." (PMID 36632137, 2023). "Decreased K48‐linked ubiquitination on GRB2 induced by PSMD14 increases the stability and protein level of GRB2, promoting hepatocellular carcinoma progression." (PMID 34382324, 2021). "MiR-564 inhibited hepatoma cell proliferation, and restoration of GRB2 expression reversed the inhibitory effects of miR-564 (P < 0.05)." (PMID 29296185, 2017). "Association of GRB2 and GAB1 expression with clinicopathological features of 130 hepatocellular carcinoma patients." (PMID 24391994, 2013). "Additionally, PSMD14 can accelerate hepatocellular carcinoma development and metastasis by stabilizing GRB2." (PMID 36959615, 2023). "To explore the key targets and signaling pathways of Ansofaxine hydrochloride for inhibiting hepatocellular carcinoma, we first dock SRC, GRB2, PIK3R1, AKT1, and EGFR, which are in the front of the core genes." (PMID 40809022, 2025). "Inhibition of ERK1/2 mediated by RSV has been demonstrated in multiple cancer cell lines, including rat hepatoma cells (H4IIE), through mechanisms involving activation of PP2A and PTEN, as well as dissociation of IRS, PI3K, and Grb2." (PMID 40806567, 2025). "Increased stability of GRB2 and TGF‐β receptors induced by PSMD14 overexpression can hyperactivate their signaling to enhance hepatocellular carcinoma growth and metastasis." (PMID 34382324, 2021). "Furthermore, the analysis of human hepatocellular carcinoma specimens obtained from the GEO database showed that the expression of EGFR and Met correlated with that of Grb2." (PMID 29575431, 2018). "In hepatoma cells expressing GHSR1a, ghrelin stimulates the MAPK signaling pathway characterized by Tyr phosphorylation of insulin receptor substrate-1 (IRS-1) and binding of growth factor receptor-bound protein 2 (GRB2) to IRS-1, an upstream signaling molecule of MAPK." (PMID 24651458, 2014). "Taken together, these results demonstrated that sinulariolide could inhibit hepatocellular carcinoma cell migration and invasion and alter HA22T cell metastasis by reduction of MMP-2, MMP-9, and uPA expression through the suppression of MAPKs, PI3K/Akt, and the FAK/GRB2 signaling pathway." (PMID 26204832, 2015).
lung cancer (19 papers, 2013 to 2025). A malignant neoplasm involving the lung. "Previous studies have shown that Grb2 can modulate EMT via the Snail transcription factor and via the SHP2/Grb2/PI3K/AKT signaling cascade in lung cancer." (PMID 38985526, 2024). "Consistently, we observe that TGF-β1 promotes the activation of the SHP2/Grb2 axis in lung cancer cells." (PMID 35589677, 2022). "Altogether, these results prove that SH2B3 inhibits anoikis resistance, EMT, cell proliferation, migration, and invasion of lung cancer via suppressing SHP2/Grb2/PI3K/AKT signaling." (PMID 35589677, 2022). "Prior studies have shown that an imbalance in the GRB2 level in tumors can influence the invasion and metastasis of tumor cells in malignancies, such as in liver cancer and lung cancer 23,24." (PMID 34729100, 2021). "In non–small-cell lung cancer, Grb2 is involved in tumor metastasis by regulating both MAPK and Akt pathways." (PMID 34305583, 2021). "The epidermal growth factor receptor (EGFR), a known lung cancer driver, and the growth factor receptor-bound protein 2 (GRB2), an adaptor protein involved in many oncogenic signaling pathways appeared as main hubs in this network." (PMID 32575471, 2020). "The role of GRB2 in anchorage-independent growth of A549 lung cancer cells was studied by carrying out a soft agar colony formation assay." (PMID 30087284, 2018). "To explore the translational application of SH2-PLA, we analyzed binding of Grb2 SH2 to EGFR in lung cancer patient tissues." (PMID 26112401, 2015). "We identified ARHG5 from the lung cancer cell line TAP data as prey proteins of GRB2 and SHC1 baits." (PMID 24189400, 2013). "Besides JAK2/STAT3 signaling, we also demonstrate that SH2B3 interacts with SHP2 to inhibit the SHP2/Grb2/PI3K/AKT signaling pathway in lung cancer cells." (PMID 35589677, 2022). "To investigate the molecular mechanisms underlying the function of the TGF-β1/SH2B3 axis in lung cancer, we next determined whether and how TGF-β1 modulated JAK2/STAT3 and SHP2/Grb2/PI3K/AKT signaling." (PMID 35589677, 2022). "In addition, it suppresses lung cancer proliferation and induces apoptosis by modulating the GRB2/Ras/Erk pathway." (PMID 33613755, 2021). "The ability of GRB2 to enhance TGF-β1-induced EMT, expression of mesenchymal transcription factor SNAIL, migration, invasion and anchorage-independent growth in A549 lung cancer cells led us to further investigate the role of GRB2 in in vivo metastatic progression." (PMID 30087284, 2018). "Its ten hub genes were extracted and confirmed in the literature; seven of them (UBC, SRC, SP1, MYC, STAT3, RB1, and MAPK1) were verified to be associated with lung cancer, while the remaining three genes, JUN, NR3C1, and GRB2, were potentially new candidate lung adenocarcinoma-related genes." (PMID 26402252, 2015). "Therefore, we can conclude that in lung cancer cells, Grb2, SCOS and PKCμ are the potential target molecules for SIPA1, thus promoting the recycling of MET, in order to maintain the MET receptor at a high level, thereby enabling the transmission of the HGF signal within the cells." (PMID 33917539, 2021). "We discovered that while Grb2 and cortactin are present to a lesser degree in the Tks4-formed complex, CD2AP and CAPZA1 are abundant in the tested three lung cancer cell lines." (PMID 38985526, 2024). "In conclusion, SH2B3 restrained the development of anoikis resistance and EMT of lung cancer cells via suppressing JAK2/STAT3 and SHP2/Grb2/PI3K/AKT signaling cascades, leading to decreased cancer cell proliferation, migration, and invasion." (PMID 35589677, 2022). "In summary, our study is the first to illustrate the crucial roles of SH2B3 in lung cancer and reveals that TGF-β1/SH2B3 axis regulates the anoikis resistance and EMT process of lung cancer cells via JAK2/STAT3 and SHP2/Grb2/PI3K/AKT signaling pathways." (PMID 35589677, 2022).
lung cancer (continued). "A549GRB2 cells were highly invasive, while A549GRB2KD cells exhibited reduced migratory and invasive characteristics, suggesting that GRB2 promotes EMT and invasion in A549 lung cancer cells." (PMID 30087284, 2018). "In summary, we have shown, for the first time, that overexpression of GRB2 reduces E-cadherin expression, one of the hallmarks of EMT, in A549 lung cancer cells." (PMID 30087284, 2018). "For each unit increase in the relative expression of the DUSP6, GRB2, and MDM2 genes, the odds of having lung cancer increased by 7.71, 7.41 and 5.36, respectively." (PMID 27418131, 2016). "GRB2, SHC1, ERRFI, and UBS3B were found both in EGFR-mutant lung cancer cell lines and in AALE cells with mutant EGFR as a bait and thus represented logical choices to further examine as secondary baits." (PMID 24189400, 2013). "Mutant EGFR pulldowns identified MAPK adaptors GRB2 and SHC1 as well as ERRFI and UBS3B tyrosine phosphatase, all consistent with our results described in the lung cancer cell lines harboring mutant EGFR." (PMID 24189400, 2013). "In this study, we hypothesized that TGF-β1/SH2B3 axis participated in lung cancer development by modulating JAK2/STAT3 and SHP2/Grb2 signaling pathways." (PMID 35589677, 2022). "Various receptor tyrosine kinases such as Epidermal Growth Factor Receptor (EGFR), HGFR/c-Met along with their downstream signalling molecules, such as GRB2, mitogen-activated protein kinase (MAPK), and Phosphoinositide 3-kinase (PI3K), have been found to be over-expressed in lung cancer." (PMID 30087284, 2018). "The role of GRB2 in lung cancer has not been well characterised; thus, the expression and localisation of GRB2 during TGF-β1-induced EMT in A549 cells was investigated." (PMID 30087284, 2018). "However not much is known about the role of GRB2 in EMT during lung cancer progression." (PMID 30087284, 2018).
gastric cancer (14 papers, 2009 to 2025). A primary or metastatic malignant neoplasm involving the stomach. "For instance, the level of miR-433 is decreased in human gastric carcinoma, which is associated with unfavorable outcome in overall survival, and GRB2 and KRAS are direct target of miR-433 in human gastric carcinoma." (PMID 27926502, 2017). "Studies have reported that increased expression and overexpression of Grb2 relate to poor prognosis in patients with gastric cancer and lymph node metastasis and poor survival in esophageal cancer patients, respectively." (PMID 37687413, 2023). "Meanwhile, we confirmed that RAB34, GRB2 were down regulated by miR-9 and miR-433 respectively, which revealed the potential mechanism for gastric carcinoma genesis." (PMID 19531230, 2009). "Recent studies have highlighted the aberrant expression of GRB2 across multiple malignancies, including HCC, glioblastoma, colorectal carcinoma, cholangiocarcinoma, pancreatic ductal adenocarcinoma, and gastric cancer." (PMID 40883741, 2025). "In the process of gastric cancer cell migration, EGF activates EGFR, which through the combination of Grb2 and DENND1A plays a role in target molecule activation and targeted recruitment." (PMID 30524285, 2018). "In view of this, our studies in gastric cancer have shown that DENND1A exerts GEF action during the activation of Rab35 stimulated by EGF, and through its interaction with Grb2, it can regionally recruit activated Rab35 and then promote the migration of tumor cells." (PMID 30524285, 2018).
ovarian carcinoma (14 papers, 2015 to 2025). A malignant neoplasm originating from the surface ovarian epithelium. "Given our findings in ErbB2 mutated or amplified ovarian cancer cell lines, we hypothesized that Grb2 was a critical mediator of oncogenic signaling in uterine carcinomas." (PMID 32754300, 2020). "Finally, we found ovarian cancer cell lines with ErbB2 mutations or overexpression to be particularly sensitive to Grb2 downregulation." (PMID 32754300, 2020). "In a GRB2-depleted syngeneic ovarian cancer mouse model, PARPi treatment led to enhanced targeted destruction of tumor cells by the host immune system compared to PARPi alone." (PMID 38459011, 2024). "Our prior cancer database analyses suggested that ovarian cancer with low GRB2 expression correlated with increased cytotoxic T-cell infiltration." (PMID 38459011, 2024). "We first performed a L-Grb2 dose-finding experiment using the OVCAR5 ovarian cancer mouse model and measured Grb2 protein expression in harvested tumors at 24 and 72 hours after L-Grb2 administration." (PMID 32754300, 2020). "Next, to understand the broader downstream effects of Grb2 inhibition on ovarian cancer cells, we conducted a RPPA analysis with OVCAR8 cells." (PMID 32754300, 2020). "Reverse phase protein array analysis identified significant dysregulation of metabolites (LDHA, GAPDH, and TCA intermediates) in ovarian cancer cells after Grb2 downregulation." (PMID 32754300, 2020). "Vimentin, only identified in ovarian cancer cells; growth factor receptor-bound protein 2, only identified in colorectal cancer cells; and glutathione-S-transferase π, identified in all four cell lines, were further investigated." (PMID 32466394, 2020). "In ovarian cancer, GRB2 maintains replication fork stability by inhibiting RAD51 ATPase activity, preventing cytosolic DNA release that activates cGAS‐STING; GRB2 deficiency allows PARP inhibitors (PARPis) to induce DNA fragment release and enhance antitumour immunity." (PMID 41350246, 2025). "miR-378a-3p could bind to the target genes, mitogen-activated protein kinase 1 (MAPK1) and growth factor receptor bound protein 2 (GRB2), leading to the silencing of their expression and reversing the cisplatin resistance of ovarian cancer cells." (PMID 34749775, 2021). "The high prevalence of molecular alterations in the MAPK and PI3K/AKT/mTOR pathways in ovarian carcinomas suggest that targeting Grb2 could be an important and promising therapeutic opportunity." (PMID 32754300, 2020). "Next, we examined the effect of Grb2 downregulation on ovarian cancer cell proliferation." (PMID 32754300, 2020). "Moreover, GRB2, an important upstream factor in MAPK/Erk signaling pathways, was reported to have implicated in resistance of ovarian cancer to cisplatin by activating MAPK/Erk signaling pathways." (PMID 29416005, 2018). "By targeting mitogen-activated protein kinase 1 (MAPK1)/growth factor receptor bound protein 2 (GRB2), MiR-378a-3p makes ovarian cancer cells more sensitive to cisplatin." (PMID 35412951, 2022). "miR-378a-3p decreases interleukin-33 levels and enhances the sensitivity of ovarian cancer cells to cisplatin through targeting MAPK1 and GRB2." (PMID 35791446, 2022). "Ovarian cancer cells with ErbB2 amplification (OVCAR8 and SKOV3ip1) were the most sensitive to Grb2 downregulation." (PMID 32754300, 2020). "Altogether, our findings show that overexpression of miR-634 leads to direct repression of RSK2, CCND1, GRB2 and ERK2 in ovarian cancer cell lines and ovarian cancer cells derived from patients." (PMID 26576679, 2015). "We measured the baseline expression of Grb2 in a panel of seven ovarian cancer cell lines and compared it with that in the non-transformed ovarian cell line HIO180." (PMID 32754300, 2020). "We show that miR-634 regulates cyclin D1 and several Ras-MAPK pathway components (GRB2, ERK2, RSK1 and RSK2), which may contribute to the effects of miR-634 on ovarian cancer cell survival and chemotherapy response." (PMID 26576679, 2015).
ovarian carcinoma (continued). "In addition, we observed that miR-634 overexpression in ovarian cancer cell lines and patient samples negatively regulates important cell-cycle genes (CCND1) and Ras-MAPK pathway components (GRB2, ERK2, RSK1 and RSK2)." (PMID 26576679, 2015).